KLHL40 (kelch like family member 40)
Description:
Substrate-specific adapter of a BCR (BTB-CUL3-RBX1) E3 ubiquitin ligase complex that acts as a key regulator of skeletal muscle development. The BCR(KLHL40) complex acts by mediating ubiquitination and degradation of TFDP1, thereby regulating the activity of the E2F:DP transcription factor complex (By similarity). Promotes stabilization of LMOD3 by acting as a negative regulator of LMOD3 ubiquitination; the molecular process by which it negatively regulates ubiquitination of LMOD3 is however unclear (By similarity).
Synonyms: KBTBD5; SRYP; NEM8; SYRP
Tractability: Small molecule: it belongs to a druggable protein family.
Gene: Protein-coding gene on chromosome 3 (42,685,447 to 42,695,064, forward strand). Ensembl gene ENSG00000157119.
Subcellular location: Cytoplasm; Cytoplasm, myofibril, sarcomere, A band; Cytoplasm, myofibril, sarcomere, I band
Gene Ontology:
Molecular function: protein binding; ubiquitin-like ligase-substrate adaptor activity
Biological process: negative regulation of proteasomal ubiquitin-dependent protein catabolic process; negative regulation of protein ubiquitination; positive regulation of proteasomal ubiquitin-dependent protein catabolic process; positive regulation of protein ubiquitination; proteasome-mediated ubiquitin-dependent protein catabolic process; skeletal muscle fiber development; skeletal muscle fiber differentiation
Cellular component: A band; Cul3-RING ubiquitin ligase complex; cytoplasm; I band
Genetic constraint (gnomAD): Loss-of-function variants: 41 observed, 47.15 expected, observed/expected ratio (o/e) 0.87, 90% interval 0.68 to 1.13. The upper end of that interval is the gene's LOEUF score, 1.13, which puts it in group 4 of 6, group 1 being the genes least tolerant of losing a copy. Missense variants: 868 observed, 840.95 expected, observed/expected ratio (o/e) 1.03, 90% interval 0.98 to 1.09. Synonymous variants: 396 observed, 368.09 expected, observed/expected ratio (o/e) 1.08, 90% interval 0.99 to 1.17.
Gene-disease validity (ClinGen):
ClinGen rates the evidence that KLHL40 causes each of these diseases.
nemaline myopathy 8 (autosomal recessive): Definitive. An autosomal recessive myopathy caused by mutations in the KLHL40 gene, encoding Kelch-like protein 40.
Homologues: Orthologues: chimpanzee KLHL40 (99% identical), macaque KLHL40 (99% identical), rabbit KLHL40 (95% identical), dog KLHL40 (95% identical), pig KLHL40 (94% identical), mouse Klhl40 (92% identical), rat Klhl40 (92% identical), guinea pig KLHL40 (91% identical), tropical clawed frog klhl40 (67% identical), zebrafish klhl40a (59% identical), zebrafish klhl40b (57% identical). Paralogues in human: KLHL41 (49% identical), KLHL20 (27% identical), KLHL17 (25% identical), KLHL35 (25% identical), KLHL2 (25% identical), KLHL3 (24% identical), KLHL6 (24% identical), KLHL21 (24% identical), KLHL24 (24% identical), KLHL4 (24% identical), KLHL18 (24% identical), KLHL1 (24% identical), and 42 more.
Diseases named in the same sentence as KLHL40 in open-access papers:
KLHL40 is named in the same sentence as 23 diseases in open-access papers, as found by Europe PMC text mining. Sharing a sentence is not in itself a finding about the gene and the disease. The quoted sentences say what the papers report.
nemaline myopathy (19 papers, 2014 to 2025). Nemaline myopathy (NM) encompasses a large spectrum of myopathies characterized by hypotonia, weakness and depressed or absent deep tendon reflexes, with pathologic evidence of nemaline bodies (rods) on muscle biopsy. "Nemaline myopathy due to mutations in KLHL40 is the most common form of severe nemaline myopathy and represents a rather homogeneous entity from both a clinical and genetic perspective." (PMID 38397198, 2024). "We performed global proteomic and ubiquitylome profiling of skeletal muscle during development and disease progression in a Klhl40 deficient zebrafish model of congenital nemaline myopathy." (PMID 37432316, 2023). "Similar to mutations in the NEB exon 143-144 region, KLHL40 deficiency is associated with nemaline myopathy." (PMID 37576554, 2023). "KLHL40 deficiency in humans results in a severe form of nemaline myopathy associated with neonatal lethality." (PMID 37432316, 2023). "The novel variant in the NEB gene resulted in a classical type 2 nemaline myopathy, while the KLHL40 gene variant led to a severe phenotype of nemaline myopathy, type 8." (PMID 37025449, 2023). "We were also able to identify two fetuses with the Chinese-specific founder mutation, KLHL40 (Kelch-like family member 40) c.1516A>C, which causes one of the most severe forms of nemaline myopathy (OMIM#615340)." (PMID 36554045, 2022). "Autosomal recessive or compound heterozygous mutations in KLHL40 cause nemaline myopathy 8, which is one of the most severe forms of nemaline myopathy." (PMID 32352246, 2020). "We reported six cases from five unrelated families of non‐consanguineous southern Chinese affected by nemaline myopathy 8, with either homozygous variants or compound heterozygous variants involving c.1516A>C in KLHL40." (PMID 32352246, 2020). "In a large cohort of patients, KLHL40 autosomal recessive mutations (NEM8) were identified as a frequent cause of severe nemaline myopathy, even with prenatal symptoms and unfavourable outcome." (PMID 32456280, 2020). "LMOD3 biopsies have been reported to show rods with a fringe of myofibrils attached, but we have observed similar rods associated with other nemaline myopathy gene mutations, in particular KLHL40." (PMID 31228046, 2019). "KLHL40 mutations have been recently identified as a cause of nemaline myopathy in a severe form of the disease." (PMID 24959344, 2014). "Unlike KLHL9 and KBTBD13 mutations that cause a dominant form of the disease, mutations in KLHL41, like KLHL40, result in an autosomal recessive form of nemaline myopathy." (PMID 24959344, 2014). "Furthermore, loss of KLHL40 results in a severe lethal form of nemaline myopathy associated with destabilization of actin." (PMID 34433058, 2021). "More recently, KLHL41 (kelch like family member 40) mutations, encoding for nebulin-interacting homonymous protein, which is important in myofibril maturation, are also associated with mainly severe early onset forms of nemaline myopathy." (PMID 32456280, 2020). "For partial effect non-coding variants that do cause disease, they may result in milder phenotypes, for example, variants in the CDS of KLHL40 are linked to severe forms of nemaline myopathy, whereas a variant in the 5′UTR of KLHL40 is linked to a milder form of disease." (PMID 40610610, 2025). "Additionally, we identified a 3′ UTR variant in KLHL40 in a patient with nemaline myopathy 8 and a missense variant in YARS2 in a patient with a mitochondrial disorder known as MLASA2, both of which Introme helped prioritise as candidate splice-altering variants." (PMID 37198692, 2023). "Nemaline myopathy 8 (MIM #615348), caused by biallelic pathogenic variants in KLHL40, is one of the most severe forms of NEM." (PMID 35379254, 2022). "Similarly, mutations in Kelch repeats of both KLHL40 or KLHL41 also result in nemaline myopathy." (PMID 24959344, 2014).
nemaline myopathy (continued). "Several genes among the Kelch-like family members are involved in nemaline myopathy; Kelch-like protein 40 (KLHL40) decreases thin filament protein stability, KBTBD13 disorganises the Z-disc, and Kelch-like protein 41 (KLHL41) impacts on nebulin degradation." (PMID 32938372, 2020). "In turn, KLHL40 is suggested to stabilize nebulin and Leimodin 3 (LMOD3, another protein implicated in nemaline myopathy) by acting like a chaperone and maintaining proper folding of these two proteins during muscle contraction." (PMID 32660935, 2020). "KLHL40 (formerly, KBTBD5), another gene that can contain recessive mutations causing nemaline myopathy, is the second most highly expressed KLHL gene in SkM (TPM, 302)." (PMID 33182325, 2020). "Evidence for the functional significance of BACK domains comes from recent studies where missense mutations in this domain in KLHL40 and KLHL41 are pathogenic in human patients affected with nemaline myopathy." (PMID 24959344, 2014). "An amino acid alignment of only the Kelch repeat regions shows that proteins involved in similar disease processes are clustered together (for example, KLHL40, KLHL41, and KBTBD13, all of which cause nemaline myopathy)." (PMID 24959344, 2014). "However, considering the absence of severe or moderate side effects, the use of pyridistogymn in KLHL40-related nemaline myopathies should be proposed." (PMID 38397198, 2024). "However, in a later clinical reassessment, the detection of rods in a second muscle biopsy and further genetic investigations led to the conclusive diagnosis of KLHL40-related nemaline myopathies." (PMID 38397198, 2024). "KLHL9, KBTBD13, KLHL40, and KLHL41 have been implicated in distal and nemaline myopathy." (PMID 31985165, 2020). "A significant number of patients with KLHL40 mutations (approximately 17%) also exhibit ophthalmoparesis that is usually not present in other genetic subtypes of nemaline myopathy." (PMID 24959344, 2014). "Mutations in KLHL40, a CUL3 family E3 substrate adaptor protein, have been reported to result in server congenital nemaline myopathy (NM)." (PMID 37432316, 2023). "As most of the previously known NM proteins are components of sarcomeric thin filaments, the unique localization of KLHL41, as well as non-sarcomeric localization of KLHL40 in association with the triads, suggests the involvement of new pathophysiological mechanisms for nemaline myopathy." (PMID 24959344, 2014). "Mouse models of KLHL40 and KLHL41 nemaline myopathy showed early lethality (within days to weeks from birth)." (PMID 31228046, 2019).
congenital myopathies (6 papers, 2014 to 2023). "We suggest that KLHL40 c.1516A>C variant should be considered in prenatal diagnosis of Chinese pregnant patients with suspected congenital neuromuscular disorders or with significant family history of congenital myopathies." (PMID 32352246, 2020). "Analysis of the KLHL40 c.1516A>C variant should be considered in prenatal diagnosis of Chinese pregnant patients with suspected congenital neuromuscular disorders or with significant family history of congenital myopathies." (PMID 32352246, 2020). "We strongly suggest that KLHL40 be included in a carrier screening panel and as in first-tier testing of severe neonatal myopathy in ethnic Chinese patients, especially those with a significant family history of congenital myopathies." (PMID 35379254, 2022). "In particular, KLHL40 and KLHL41, that functions as substrate-specific adaptors for E3 ubiquitin ligase CUL3, contribute to severe forms of congenital myopathy with neonatal lethality with extensive sarcomeric disarray and contractures." (PMID 37432316, 2023).
congenital nemaline myopathy (4 papers, 2017 to 2024). A rare genetic muscle disorder defined by muscle weakness and the presence of fine, thread-like or rod-like structures called “nemaline bodies”, when muscle biopsies are viewed under the microscope. "Hedgehog acyltransferase like (HHATL) is needed for normal postnatal skeletal muscle maturation while mutation of KLHL40 is linked to Nemaline Myopathy 8 and Severe Congenital Nemaline Myopathy reflecting the role of KLHL40 in regulating skeletal muscle development." (PMID 33182325, 2020).
nemaline myopathy 8 (4 papers, 2020 to 2025). "A candidate variant, classified as likely pathogenic, was found in homozygosity in the gene KLHL40 in the fetus, leading to the diagnosis of nemaline myopathy 8 (OMIM #615348), which is inherited in an autosomal recessive manner." (PMID 39999070, 2025). "Homozygous or compound heterozygous variants in the KLHL40 gene cause nemaline myopathy 8 (NEM8), a severe autosomal recessive muscle disorder characterized by prenatal polyhydramnios, fetal akinesia or hypokinesia, joint contractures, fractures, respiratory failure and dysphagia." (PMID 35379254, 2022). "Mutations in the KLHL40 gene were related to severe nemaline myopathy type 8 (NEM8; MIM 615348) with recessive inheritance, including clinical signs of akinesia, arthrogryposis, hypotonia, chest deformities, respiratory problems, and fractures, leading to death in early childhood." (PMID 36292632, 2022).
arthrogryposis (2 papers, 2021 to 2022). A rare, non-progressive congenital disorder characterized by multiple joint contractures which are present at birth. "Four cases with arthrogryposis were screened and categorized as neuromuscular abnormalities, and the diagnostic yield was 50% (2/4) with variants in KLHL40 (case 26) and ZC4H2 (case 91)." (PMID 34367232, 2021). "These four altered genes (TPM2, KLHL30, KLHL40, and CACNA1S), detected using WES, are expressed in the muscle and have been associated in the literature with akinesia, NM, and arthrogryposis." (PMID 36292632, 2022).
centronuclear myopathy (2 papers, 2022 to 2023). Centronuclear myopathy (CNM) is an inherited neuromuscular disorder characterized by clinical features of a congenital myopathy and centrally placed nuclei on muscle biopsy. "This increased expression of SAR1A is specific to KLHL40-deficient skeletal muscle as analysis of skeletal muscle from centronuclear myopathy patients (RYR1 or MTM1 disease-causing mutations) showed no changes in the SAR1A protein levels compared to the control." (PMID 37432316, 2023). "It has been reported that severe neonatal bulbar and respiratory muscle involvement occurs particularly in severe NM (most likely ACTA1-, NEB- or KLHL40-related) and MTM1-related myotubular myopathy." (PMID 35081925, 2022).
arthrogryposis multiplex congenita (1 paper, 2022). Arthrogryposis multiplex congenita (AMC) is a group of disorders characterized by congenital limb contractures. "We report the case of a fetus with NM due to KLHL40 gene variation leading to arthrogryposis multiplex congenita (AMC)." (PMID 35928692, 2022).
floor of mouth cancer (1 paper, 2020). "3-mRNA (TGFBR3、KLHL40 and HOXC13) model was identified in the network and that was associated with the clinical outcome of floor of mouth cancer according to univariate and multivariate Cox proportional regression analyses." (PMID 32931492, 2020).
muscle disorder (1 paper, 2022). "NEM8 is considered to be a very rare autosomal recessive muscle disorder, with only 46 NEM8 individuals being reported worldwide; 30 variants in KLHL40 have been identified to date." (PMID 35379254, 2022).
sarcopenia (1 paper, 2025). Progressive decline in muscle mass due to aging which results in decreased functional capacity of muscles. "Given that sarcopenia, the progressive loss of skeletal muscle mass and function, is a major hallmark of ageing, the presence of age-correlated methylation changes in KLHL40 supports the hypothesis that epigenetic drift with age may impact key developmental and maintenance pathways in muscle tissue." (PMID 40700041, 2025).
myopathy (6 papers, 2019 to 2024). A disease of the muscle in which the muscle fibers do not function properly. "The aim of this review was to describe the cases of KLHL40-related myopathy thus far reported in the literature, including a girl harboring a homozygous mutation (c.1582G>A/p.E528K in KLHL40) who has been followed at our Institute for 12 years." (PMID 38397198, 2024). "The aim of this paper was to systematically review the cases described in the literature and to describe a 12-year clinical and imaging follow-up in an Italian patient with KLHL40- related myopathy in order to suggest possible follow-up measurements." (PMID 38397198, 2024). "Recently, it has been reported that a patient with KLHL40-related myopathy due to the c.604delG/p.Ala202Argfs*56 and c.1513G>C/p.Ala505Pro mutations responded extremely well, and for a prolonged period, to a high dose of pyridostigmine (20 mg/kg/day)." (PMID 38397198, 2024). "KLHL40 (kelch-like family member 40) results in a nemaline-like myopathy in mice that closely phenocopies muscle abnormalities observed in KLHL40-deficient patients, leading to muscle weakness characteristics as well." (PMID 37239410, 2023). "The peptides in the super repeat region of nebulin are binding sites for kelch like family member 40 (KLHL40), loss of which causes a nemaline-like myopathy." (PMID 32660935, 2020). "Twenty-eight patients had a family history of KLHL40-related myopathy (43%)." (PMID 38397198, 2024).
neuromuscular disease (3 papers, 2015 to 2024). "The study has also resulted in the identification of four novel neuromuscular disease genes, and has led to the identification of a novel mechanism of sarcomere assembly and muscle dysfunction involving KLHL40, KLHL41 and LMOD3." (PMID 26578207, 2015). "Mutations were found in eight previously known neuromuscular disease genes (CHRND, CHNRG, ECEL1, GBE1, MTM1, MYH3, NEB and RYR1) and four novel neuromuscular disease genes (GPR126, KLHL40, KLHL41 and SPEG)." (PMID 26933539, 2015). "The study also led to the identification of novel neuromuscular disease genes (KLHL40, KLHL41, and LMOD3) involved in sarcomere assembly and muscle dysfunction." (PMID 26933539, 2015). "Within this cohort, mutations were found in eight previously known neuromuscular disease genes (CHRND, CHNRG, ECEL1, GBE1, MTM1, MYH3, NEB and RYR1) and four novel neuromuscular disease genes were identified and have been published as separate reports (GPR126, KLHL40, KLHL41 and SPEG)." (PMID 26578207, 2015). "Four novel genes related to neuromuscular diseases were found, consisting of GPR126, KLHL40, KLHL41, and SPEG genes." (PMID 37989827, 2024).
KLHL40 also shares sentences with these, for which no sentence is quoted: respiratory failure (2 papers); alcohol-dependent (1); Atrophy (1); autosomal recessive nemaline myopathy (1); cardiomyopathy (1); distal myopathy (1); epidermolysis bullosa simplex (1); inherited diseases (1); myocardial infarction (1); pontocerebellar hypoplasia, type 1C (1); type 2 nemaline myopathy (1).